CD4 (CD4 molecule)
Diseases named in the same sentence as CD4 in open-access papers (continued):
Sharing a sentence is not in itself a finding about the gene and the disease.
Opportunistic infection (continued). "In fact, HTLV-1-induced expansion of CD4+ cells can lead to misleadingly high CD4+ counts, masking underlying immune dysfunction and increasing the risk of opportunistic infections, including disseminated tuberculosis and cerebral toxoplasmosis, even at ostensibly protective CD4+ levels." (PMID 40431676, 2025). "For instance, the number of CD4 lymphocytes may be of prognostic significance, particularly in the context of the risk of opportunistic infections." (PMID 41465777, 2025). "Consequently, opportunistic infections associated with low CD4+ T-cell counts, including NTM infections, are more frequently reported in patients receiving long-term corticosteroid therapy." (PMID 41583153, 2025). "In the bivariable analysis, variables including sex, presence of opportunistic infections or cancers, current CD4 count, viral load, duration since HIV diagnosis, loss of biological relatives, perceived stigma, social support, smoking, and khat chewing had p-values less than 0.25." (PMID 40485941, 2025). "Although this explanation needs further investigation, this could be due to the depressed immunity of the patients implying that as the CD4+ counts decline, the risk of UTIs and broadly opportunistic infections also increases." (PMID 38678188, 2024). "A low CD4 count is often associated with a high probability of opportunistic infections, which may contribute to treatment failure." (PMID 38652716, 2024). "This might be because low CD4 count might be associated with opportunistic infections, which further bring additional worries, stress and physical disabilities." (PMID 38238489, 2024). "The elevated SMR in women may also stem from the higher likelihood of delayed diagnosis among women as reported in the World Health Organization European Region, with lower CD4 cell counts and an increased risk of opportunistic infections." (PMID 38560603, 2024). "As CD4 is not expressed on HSCs, depletion may be reversible, reducing the risk for prolonged CD4 T cell aplasia, which can be fatal secondary to opportunistic infections." (PMID 39095991, 2024). "This is due to white blood cells called CD4 cells aid in the activation of other white blood cells in the immune system when being with CD4 count below threshold is the very indicative of low immunity and increase susceptibility for opportunistic infections such as pneumonia." (PMID 39232814, 2024). "When considering an appropriate CD4 + T-cell count threshold for implementing this diagnostic package for opportunistic infections, program planners must balance the burden of AHD and of the targeted OIs, while also considering the cost implications for HIV programs." (PMID 38627642, 2024). "Moreover, we did not access studies in our literature search, which reported the association of CD4, opportunistic infections, and viral load with dyslipidemia or any lipid abnormalities." (PMID 38722964, 2024). "Determining the right CD4 + T-cell count threshold for integrating a diagnostic package for opportunistic infections requires a detailed assessment of the local burden of AHD, the frequency of OIs being targeted, and the cost implications and cost-effectiveness for the HIV program." (PMID 38627642, 2024). "Furthermore, lower CD4+-T-cells are known to be a risk factor for the development of herpes zoster virus reactivation in MM patients receiving bortezomib, as well as for opportunistic infections in patients with MM receiving conventional therapy." (PMID 37152008, 2023). "The loss of CD4+ T cells following primary or secondary immunodeficiencies has highlighted the critical importance of T cell help in preventing allergies, autoimmunity, and opportunistic infections." (PMID 37892982, 2023). "One of the most important mechanisms may be preventing HIV-mediated CD4 T-cell depletion, which increases the risk for opportunistic infections and malignancies." (PMID 37735371, 2023).
Opportunistic infection (continued). "The effect of low CD4 counts makes patients more susceptible to opportunistic infections, which could increase the chance of virological failure." (PMID 37085851, 2023). "PLHIV with severe immune impairment were prone to maintain high VL for a long time and suffer from opportunistic infections, and lower baseline CD4 counts may be associated with a reduced CD4 cell response to HAART." (PMID 37130123, 2023). "The hallmark of HIV infection is the depletion of CD4+T lymphocytes, eventually leading to defective cell-mediated immunity, which is significant enough and may lead to various opportunistic infections." (PMID 37108634, 2023). "Concurrent pneumocystis pneumonia may reflect the low CD4 cell count and may put patients at risk of other opportunistic infections during a 1-year period and may lead to higher mortality." (PMID 36986349, 2023). "Furthermore, the NDoH guidelines only describe the use of CD4 count monitoring to determine susceptibility to opportunistic infections and the need for possible prophylactic treatment." (PMID 38633911, 2023). "This could be explained by a lower CD4 count will increase the risk of opportunistic infection which will further complicate treatment outcomes." (PMID 38033131, 2023). "Furthermore, this implies that more consideration should be given to patients with low CD4+ T cell counts who are in a critical condition, as they have an increased opportunistic infection risk, with lower levels of antiviral immune surveillance." (PMID 36675642, 2023). "The underlying factors for opportunistic infections might be attributed to the drop of CD4+ T-cell counts below 250 cells/mm3." (PMID 36232165, 2022). "The underlying factors for opportunistic infections might be attributed to the condition of less than 250 CD4+ T cells/mm3." (PMID 36231240, 2022). "Furthermore, children with lower CD4 cell count and history of opportunistic infections were found to be at high risk to develop HIV treatment failure." (PMID 35421084, 2022). "HIV mainly invades human CD4+ T lymphocytes, causing a reduction in their number and functional defects, thereby resulting in low immune function and an increasing incidence of various opportunistic infections." (PMID 34917092, 2021). "High serum IgM levels associated with high smB cells has been linked to higher incidence of B-cell lymphoma’s in CVID17,39, while CD4+ T-lymphocytopenia may add on susceptibility risk of opportunistic infections in a subset of CVID patients." (PMID 34108596, 2021). "In‐person visits in ID clinics were restricted to patients with urgent care needs without COVID‐19 symptoms, patients presenting for same day ARV and routinely scheduled patients who were considered high risk (e.g., active opportunistic infections, high VL and low CD4 count)." (PMID 34713585, 2021). "This improved CD4 level is associated witha reduced number of opportunistic infections." (PMID 34972169, 2021). "Nonetheless, because we show that either CD4+ or CD8+ T cells are required, C. neoformans Δsgl1 still remains a viable option for the major risk factors during the opportunistic infection with C. neoformans since CD8+ T cells remain accessible during CD4-lymphopenia." (PMID 34568097, 2021). "This may indicate the success of ART intervention in reducing opportunistic infection including intestinal parasites among the HIV high risk group of lower CD4 count." (PMID 34178224, 2021). "Higher CD4 counts are associated with a lower probability of developing an opportunistic infection." (PMID 34187374, 2021). "The possible justification could be due to the fact that a qualitative and quantitative reduction in CD4+ T cell count due to HIV could result in increased susceptibility to opportunistic infections." (PMID 33382867, 2020). "The presence of opportunistic infections, on the other hand, linked to CD4 cell level." (PMID 31959136, 2020).
Opportunistic infection (continued). "Furthermore, absolute CD4+ T cell count during treated HIV infection is a critical clinical measure for risk of opportunistic infections." (PMID 32949118, 2020). "The immune reconstitution pattern in our cohort showed long-term decreased CD4+ T cells, which puts patients at risk for reactivations of herpes viruses and opportunistic infections, although opportunistic infections like Pneumocystis jirovecii pneumonias are scarce after aHSCT under prophylaxis." (PMID 32771029, 2020). "However, in recent studies, alemtuzumab has been found to result in long-term immunosuppression, particularly depleting CD4+ T cells, and increase the risk of opportunistic infection." (PMID 32802866, 2020). "Therefore, CD4+ T lymphocyte count remains the best indicator of a patient’s immunological and clinical status, the risk of opportunistic infections like TB, and supports diagnostic decision making, particularly for patients with advanced HIV disease." (PMID 32380957, 2020). "Lower CD4 counts are reported to be associated with an increased risk of opportunistic infection." (PMID 33777501, 2020). "This might be as CD4 cell increases, there might be reduction of viral load and it leads to reduction of opportunistic infection which caused under nutrition." (PMID 31315661, 2019). "Highly active antiretroviral therapy (HAART) causes a rapid increase of CD4 + T cells counts during the first 3–6 months of treatment and may enhance the development of opportunistic infections (OIs)." (PMID 30837537, 2019). "The association between the two variables could be due to the fact that low CD4+ T cell counts predispose HIV-infected patients to opportunistic infections because of the immunosuppression." (PMID 31805085, 2019). "HIV infection causes the depletion of CD4+ T cells and may increase the risk for opportunistic infections (OIs)." (PMID 30837537, 2019). "This might be attributed to the infectiousness properties of the TB bacilli that cause an opportunistic infection at any level CD4 count in HIV infected patients." (PMID 31675986, 2019). "This counterintuitive association is a well-known phenomenon in European and sub-Saharan cohort studies and is generally explained by a closer clinical monitoring and better adherence of patients with lower CD4 cell count who are at an increased risk for opportunistic infections." (PMID 30332404, 2018). "The CD4 count is a reflection of the patients' immune status, so when it becomes low, the risk of developing opportunistic infections will increase, which may finally lead to death." (PMID 29214077, 2017). "Furthermore, CD4+ T cell testing is an important diagnostic in supporting clinical opportunistic infection monitoring of all HIV-positive patients." (PMID 28448581, 2017). "However, the most unusual of reported infections among the HEU have been opportunistic infections, suggesting the possibility of underlying defects in CD4 helper T cells and overall immune regulatory function." (PMID 27594857, 2016). "During intercurrent illness, the CD4 count may decline and lead to increased susceptibility to opportunistic infections." (PMID 27431995, 2016). "Aggressive chemotherapy may be required to kill HTLV-1-infected CD4+ cells, but increasing the risk of opportunistic infections and further immunosuppression." (PMID 26693362, 2015). "On one hand, depletion of CD4+ T cells leads to progressive impairments in cellular immunity and increases the susceptibility to opportunistic infections, as manifested by the effects of HIV infection whose hallmark is the progressive depletion of CD4+ T cells." (PMID 25188007, 2014). "The HIV infection usually leads to a progressive decay in the functionality and number of CD4+T-cells (normally about 1000 per microlitre in blood), resulting in a consequent impairment in host immune defenses and increasing susceptibility to opportunistic infections and malignancies for patients." (PMID 24963975, 2014).
Opportunistic infection (continued). "Patients with low CD4 cell counts may be at higher risk of opportunistic infections that could affect the thyroid, such as hypothyroidism due to infiltration of Kaposi’s Sarcoma cells into the thyroid gland." (PMID 24194919, 2013). "However, most opportunistic infections are strongly associated with CD4 cell count which was adjusted for." (PMID 23418463, 2013). "Moreover, persistently low T-cell function is likely to contribute to the increased risk of opportunistic infection observed among the individuals with suboptimal CD4 reconstitution despite suppressive HAART." (PMID 23786370, 2013). "This could explain previous reports that HAART-treated individuals with poor CD4 recovery despite viral suppression were at increased risk of opportunistic infections and mortality." (PMID 23786370, 2013). "The incident pathologies associated with various immunosuppressed conditions such as those found in HIV infection have taught us that measuring various T cell populations including CD4 provides the clinician with a reliable measure for gauging the risk of cancer and opportunistic infections." (PMID 22383042, 2012). "It is possible that these opportunistic infections can cause CD4+ T lymphocytopenia." (PMID 24893304, 2012). "At least two clinical challenges relate to these patients and include the timing of HAART introduction based on the concomitant opportunistic infections and the elevated risk of failing a satisfactory CD4+ recovery, even after long-term virological suppression by HAART." (PMID 22110905, 2012). "Antiretroviral therapy has been quite successful which can be attributed to its ability to control HIV replication and preserve optimal CD4+ T helper cell population, due to which many of the opportunistic infections associated with abnormal low CD4+ T-cell counts are averted." (PMID 22666249, 2012). "The children with low CD4 count at initiation could have an increased risk of opportunistic infections which further impairs the positive effects of the ART." (PMID 22916836, 2012). "The formation of HMGB1/TLR ligand complexes has direct implications on immune activation, particularly in late stage of disease, where cell destruction and necrosis are dominant phenomena due to CD4+ T-cell loss, opportunistic infections, and other pathological conditions." (PMID 22719767, 2012). "Moreover, chronic immune activation will result in the loss of CD4+ T cells, homeostatic inbalance and T cell exhaustion, increasing the risk of disease progression and opportunistic infections." (PMID 21247613, 2011). "HIV complications associated with opportunistic infections, drug resistance, and monitoring CD4 counts, may be beyond the technical capacity of Nurse Midwives." (PMID 21992700, 2011). "Likewise, during acute HIV infection, opportunistic infections are usually associated with low CD4 cell count." (PMID 21831310, 2011). "However, a recent retrospective review suggested that delaying HAART would, particularly in those with CD4 cell counts<100 cells × 106/L, lead to significant increase in risk for death and new opportunistic infections." (PMID 16704824, 2006). "CD4+ assessment may improve risk stratification in cirrhosis; however, prospective, multicenter studies are warranted to validate these findings and to evaluate CD4-guided strategies for the prevention of opportunistic infections." (PMID 42232638, 2026). "We hypothesized that a descending gradient of CD4+ T cells count would be associated with distinct and progressively complex shifts in pathogen prevalence, thereby revealing critical risk thresholds for specific opportunistic infections." (PMID 41488483, 2025). "The most likely explanation to this may be that patients in stages III or IV are also likely to have high viral load and low CD4+ count, both of which are risk factors for development of opportunistic infections as in a study in Nigeria, which focused on CD4+ count." (PMID 38370863, 2024).
Opportunistic infection (continued). "This possible justification for this finding is that children with advanced HIV disease may have compromised immune systems due to their clinical stage III&IV, which is associated with low CD4 counts and could lead to an increased risk of developing opportunistic infections, including TB." (PMID 39093892, 2024). "CD4 cell counts may be a basic marker for patients with heightened long-term risk of opportunistic infections; however, late cases of PJP have been reported even in patients with normal CD4 counts, suggesting that the deficits in cell-mediated immunity are likely more complex." (PMID 38887472, 2024). "However, CD4 CAR-T cells can retain fratricide skills for peripheral CD4-positive T cells, which may cause CD4-positive T cell aplasia and increase the risk of opportunistic infections." (PMID 39609714, 2024). "Indeed, the CD4 cell counts were significantly higher in the contemporary cohort (median 454 vs. 140 cells/μL) and above the historical threshold for increased susceptibility to opportunistic infections (<200 cells/μL)." (PMID 37401527, 2023). "Interestingly, it has been shown in the COVID-19 pandemic that decreased CD4+-T-cells are a risk factor for a more severe course of the disease, therefore suggesting they might also facilitate non-opportunistic infections." (PMID 37152008, 2023). "The absence of significant associations between spirometric parameters and CD4 count category, viral load, or opportunistic infections suggests that while these factors play critical roles in the course of HIV infection, their direct impact on pulmonary mechanics might be more complex and nuanced." (PMID 38022158, 2023). "Moreover, in HIV-positive patients, toxoplasmosis can increase susceptibility to opportunistic infections by various mechanisms, including the depletion of CD4+ lymphocytes, decreased production of type 1 cytokines, as well as reduced activity of cytotoxic lymphocytes." (PMID 36678458, 2023). "The initiation of treatment in patients with low LT-CD4 counts is essential, especially in patients with CD4 lymphocytes <200 cells/mm3, which leads to unnecessary morbidity and mortality rates, as it exposes the individual to the risk of opportunistic infections." (PMID 37970919, 2023). "Furthermore, we speculated that opportunistic infections caused by low CD4 cell counts may be the main cause of pancreatic damage in PLWH." (PMID 36637942, 2023). "Thus, close monitoring of serum amylase may be significant in preventing opportunistic infections of PLWH, since low CD4 cell counts are associated with an increased risk of opportunistic infections." (PMID 36637942, 2023). "Deficiencies in resting CD4+ T cells may cause a predisposition to opportunistic infection, especially in the oral cavity and gastrointestinal tract, while at the same time they may reduce the viral burden by decreasing circulating target cells required for active viral replication." (PMID 37112803, 2023). "Furthermore, the risk of opportunistic infection increased with CD4 decline, which may have given patients more prompting to seek healthcare and diagnosis." (PMID 36568791, 2022). "If APH experience suboptimal CD4 counts while being virologically suppressed, that could increase their risk of experiencing opportunistic infections and advanced stage of HIV disease, especially in sub‐Saharan African settings where other infectious diseases are highly prevalent." (PMID 35255197, 2022). "Additionally, anemia has been widely reported to predict a poorer prognosis among children with HIV and TB by increasing the risk of malnutrition, CD4 count depletion, and opportunistic infection, which can result in treatment failure of antiretroviral therapy." (PMID 35241036, 2022).